IL10 (interleukin 10)
Diseases named in the same sentence as IL10 in open-access papers (continued):
Sharing a sentence is not in itself a finding about the gene and the disease.
tumor (continued). "However, also tumor cells produce many of these suppressive mediators in the TME (i.e., PD-L1, TGF-β, IL-10, PGE2) to counteract effective immune responses." (PMID 33168929, 2021). "Breg cells support carcinogenesis, tumor progression and metastasis predominantly, although not exclusively, through the production of IL-10, TGF-β, and IL-35 or by intercellular contact." (PMID 34164398, 2021). "Furthermore, the enrichment of IL-10, VEGF and prostaglandin E2 under hypoxic conditions induces Fas-ligand expression on the tumour vasculature to promote T-cells apoptosis, ultimately leading to reduced T-cell accumulation within the TME." (PMID 33923305, 2021). "CAF with tumor-promoting functions secrete growth factors (HGF, IGF1, CTGF, PDGF, VEGF, LIF), cytokines (IL-1, IL-4, IL-6, IL-8, IL-10, TGF-β), and chemokines (CCL2, CCL5, CXCL5, CXCL9, CXCL10, CXCL12), WNT5α, and bone morphogenic protein 4 (BMP4), which promote tumor progression." (PMID 35008832, 2021). "Interestingly, we observed similar IL-10 mRNA transcripts in the colon of both the WT and STAT6−/− AOM/DSS-treated mice during the advanced stages of tumor development." (PMID 33919941, 2021). "A study of DHA in melanoma showed that DHA induced the proliferation of IFN-γ+CD8+ T cells in tumor microenvironment and mouse spleens, while the number of CD4+CD25+Foxp3+ T cells and IL-10+CD4+CD25+ T cells returned to normal, thus enhancing the anti-tumor immunity of mice." (PMID 33613116, 2021). "According to recent research, exercise and hormone treatment decreased tumor growth and angiogenesis in a mouse model of invasive breast cancer by reducing levels of miR-21, ER, HIF-1, VEGF, and raising levels of miR-20 IL-10, let-7a, and PDCD4 in tumor tissue." (PMID 34778378, 2021). "IL-10 is a negative immunoregulatory cytokine for tumor immune escape, but it showed a trend of increased expression in these experiments." (PMID 33792840, 2021). "MDSCs, characterized as granulocytic/polymorphonuclear (G/PMN-MDSCs) or monocytic (M-MDSCs) based on their cell lineage of origin, further suppress the anti-tumor immune response through multiple mechanisms including the production of arginase-1, reactive oxygen species, TGF-β, and IL-10." (PMID 34831452, 2021). "The expression of the anti-inflammatory cytokine Il10 in tumor tissue was not affected by either Nrf2 disruption or genetic activation." (PMID 34526660, 2021). "Furthermore, TAMs, TILs, as well as cancer cells are also the source of IL-10 and TGF-β, amplifying their tumor promoting and tumor suppressing activity." (PMID 34336860, 2021). "IL-10 inhibits the proliferation of CD4+ T cells and its IFN-γ production, thus blocking adaptive antitumor response, and CD73 on natural killer cells increases adenosine concentration in the tumor microenvironment leading to immunosuppression." (PMID 34299305, 2021). "Furthermore, LyeTx I-b seems to be an efficient regulator of the 4T1 tumor microenvironment by modulating several cytokines, such as TGF-β, TNF-α, IL-1β, IL-6, and IL-10, in primary tumor and lung, spleen, and brain." (PMID 34572719, 2021). "We found that whole-tumor gene expression of T cell marker factors (CD8 and IFN-γ) and chemokines (CXCL9 and CXCL10) were significantly enhanced after ICT treatment, while inflammatory factors (IL6, IL10 and TNF-α) were reduced." (PMID 33460401, 2021). "In some rodent models, tumor and non-tumor cells in the TME (e.g., leukocytes, fibroblasts, endothelial cells) secrete inflammatory mediators such as interleukin (IL)-1, tumor necrosis factor (TNF)-α, IL-6, IL-8, IFN-α, IL-10, IL-12, TGF-β, and CXCR4." (PMID 34200240, 2021). "Interestingly, IL-10 increased expression of PDL1, which promotes tumor cell survival by interaction with PD1, which is an inhibitory receptor for immune cells." (PMID 34204596, 2021).
tumor (continued). "However, they were found to have in common the secretion of IL-10 and TGF-β, which renders them able to convert conventional CD4+ T cells into Tregs, and thus subvert several immune effectors at the tumor site." (PMID 33804027, 2021). "Further studies reported that increased production of IL-10 by MDSCs could inhibit the production of IL-2, IL-12 and IFN-γ by CD4+ or CD8+ T cells, which lead to their impaired proliferation and anti-tumor immunity." (PMID 35004667, 2021). "Tumor-promoting signaling molecules including transforming growth factor-β (TGF-β), IL-10, IDO, and VEGF inhibited tumor antigen presentation, as well as activation, proliferation, differentiation, and cytotoxicity of T cells, thereby limiting the efficacy of anti-tumor immunity." (PMID 34541363, 2021). "Also, it has been shown that A20 tumor cells show altered expression of the costimulatory CD80 and are a potent source of IL-10 secretion, suggesting an important immunosuppressive status that accompanies A20 cell establishment." (PMID 34413847, 2021). "In addition, tumor cells can inhibit T cell and NK cell activity by secreting MICA/B, IL-10, TGF-β, and HLA-E to recruit Tregs." (PMID 33741903, 2021). "TAMs usually have an M2 phenotype, are responsive to anti-inflammatory factors such as IL-4, IL-13 and IL-10 and secrete C-C motif chemokine ligands 2, 17 and 22 (CCL2, CCL17 and CCL22) and transforming-factor β (TGF-β), thus inducing tumor growth and dissemination." (PMID 34359591, 2021). "Since TGF-β represents an immunosuppressive effect and IL-10 is an iconic inflammatory factor of M2 macrophages 14, we speculated that TNF-α might be an important anti-tumor inflammatory factor in RIAE." (PMID 33867819, 2021). "In addition, TAMs can secrete various immunosuppressive mediators, such as interleukin-10 (IL-10), transforming growth factor-beta (TGF-β), and prostaglandin E2 (PGE2), into the TME to further inhibit anti-tumor immunity." (PMID 34552935, 2021). "We found that the LLC or B16F10 tumor-bearing mice presented the same trend, DLN derived CD8+ T cells from Ad-hTERT or IL10+Ad-hTERT-treated mice secreted significantly higher levels of IFN-γ than other groups, and these two groups showed the comparable effect." (PMID 33717103, 2021). "In many types of cancers, tumor cells secrete the chemokine CXCL12 to induce the infiltration of a large number of immature pDCs, and the cytokines of VEGF, TNF-α, TGF-β and IL-10 secreted in tumor microenvironment inhibit the maturation and activation of pDCs, then make it unable to produce IFN-α." (PMID 34737750, 2021). "An important number of cytokine levels were below the detection limit of the method (LOD and/or LLOQ) such as IL-2, IL-10, IL-11, IL-12 (p40), IL-12 (p70), IL-19, IL-27 (p28), IL-28A/IFN-λ2, IL-29/IFN-λ1, IFN-α2 and osteocalcin in both tumor and normal tissue control samples." (PMID 33846436, 2021). "Results from the two cell lines showed that the addition of IL-10 did not significantly influence the oncolytic of tumor cells by Ad-hTERT." (PMID 33717103, 2021). "In this study, increased levels of IL10, IL6 and TGFB1 correlated with an increased tumor burden." (PMID 33911154, 2021). "Schematically, they can be divided into M1-macrophages with anti-tumour activity, and M2-macrophages (CD163+), which are characterized by a pro-tumour activity through the secretion of several cytokines (IL-1, IL-6, IL-10, Vascular Endothelial Growth Factor VEGF and TGF-β)." (PMID 34206956, 2021). "Moreover, cardiolipin stimulates IL-10 secretion by activating PPAR-γ in MDSCs, which reside in the lungs of tumor-bearing mice." (PMID 34742349, 2021). "Hybridization signals (brown dots) for IL-10 or IL-6 were found in the cytoplasm of CD30-positive cells in both the BI-ALCL seroma and in the BI-ALCL xenograft, which consisted of pleomorphic tumor cells with highly atypical nuclei and prominent nucleoli encircling central necrotic areas." (PMID 33146828, 2021).
tumor (continued). "In a pilot study, I tested the in vitro toxicity of IL-10 on NXS2 and 4T1 tumor cells." (PMID 33912464, 2021). "In MIBC, the high expression of LAG3 may induce the secretion of more inhibitory cytokines, including IL-10 and TGF-β, which inhibit tumor contexture and promote tumor immune escape." (PMID 35111155, 2021). "CircCHST15 located in the cytoplasm promoted tumor growth, down-regulated the expressions of miR-155-5p and miR-194-5p, and up-regulated the expressions of PD-L1, Ki-67, PCNA, CCL17, CCL22, IFN-γ, TNF-β, and IL-10." (PMID 33777742, 2021). "Hypothetically, the inhibition of IL-10 or the coactivation of CD40, IL-12, IL-8, and TNF-α, could repolarize these macrophages to the M1 phenotype, where reverse tumor development has been demonstrated." (PMID 34177892, 2021). "Among them, cytokines with an inhibitory impact on the immune system such as IL-10 and TGFβ are of great importance: TGFβ is a pleiotropic cytokine, which potently suppresses the immune system and is secreted by a couple of TME resident and tumor cells." (PMID 34838059, 2021). "The association between the COX2 and MDSCs/Treg attractants CXCL8 and CCL22, and suppressive factors IDO1 and IL-10 were observed exclusively after the BCG treatment of human BlCa tumor tissues, but not at baseline." (PMID 33809455, 2021). "In contrast, M2 (alternatively activated) macrophages have anti-inflammatory functions, involving production of interleukin 10 (IL-10) and transforming growth factor b (TGF-b) to suppress the anti-tumor immune response and promote angiogenesis for tumor progression." (PMID 34066132, 2021). "IL10 can also induce the activation and multiplication of tumor-resident T cells without trafficking from the secondary lymphoid organs." (PMID 33381115, 2020). "In contrast, alternatively activated Mφ (M2Mφ) produce IL-10 but not IL-12 and have a reduced capacity to kill tumor cells." (PMID 32587357, 2020). "In addition, these drugs have been found to suppress the generation of Tregs, TAMs, and MDSCs at the tumor site, and to negatively regulate the expression of immunosuppressive cytokines such as TGF-β and IL-10." (PMID 32349374, 2020). "Pre-treatment with IFN-γ, the TLR3 ligand poly (I:C), and anti-IL-10 Ab, which attract IFN-γ-producing NK cell infiltration into tumor sites, rendered tumors sensitive to checkpoint blockade therapy (e.g., mAbs recognizing CTLA-4 and PD-1), leading to increased cure rates." (PMID 32714324, 2020). "After all, the tumor-draining microenvironment rather resembles reactivation in the presence of IL-10 + TGFβ, which completely failed to induce functional GzB-expressing effector T cells among LEC-educated cells." (PMID 31988323, 2020). "M2-type macrophages are featured by arginase 1 (Arg1), CD206, IL-10, and TGF-β, which may facilitate tumor progression." (PMID 32391256, 2020). "In addition, the expression of several cytokines, including interferon-γ (IFN-γ), tumor necrosis factor-α (TNF-α), interleukin-4 (IL-4), and IL-10, had been determined in the IDO shRNA-treated LLC1-tumor bearing mice in our previous study." (PMID 32933162, 2020). "Indeed, IL-10 and/or IL-6 signaling in ABC-DLBCL tumors regulate the malignant cell and tumor microenvironment, suggesting that suppression of IL-10 and IL-6 secretion is beneficial for treating ABC-DLBCL." (PMID 32391356, 2020). "Furthermore, we also found an increase in the total number of CD4+CD127lowIL-10+ T cells as well as an increase in CD4+CD127lowFOXP3+IL-10+ and CD4+CD127lowFOXP3−IL-10+ T cells in the tumor compared to healthy controls." (PMID 32100077, 2020). "It is thus not surprising to know that targeting IL-10 for inhibition in such conditions has been suggested as a therapeutic approach to enhance anti-tumour immune responses." (PMID 32931721, 2020).
tumor (continued). "Targeting both IL-10 and PD-1 by neutralizing antibodies, but not PD-1 alone, resulted in reduced tumour burden, augmented adaptive anti-tumour immunity and thus enhancement in survival of tumour-bearing mice." (PMID 32931721, 2020). "TAMs directly inhibit CTLs through immune checkpoint engagement by expressing programmed cell death ligand 1 (PD-L1) and B7-H4, secreting inhibitory cytokines IL-10 and TGF-β, and depleting metabolites such as L-arginine, which is essential for T cell fitness and anti-tumor activity." (PMID 32754274, 2020). "Treatment of mice with established B16-OVA tumors or EL4-OVA tumors with IWP-L6 or C59 delayed tumor growth, and this was due to marked increase in tumor-antigen-specific CD4+ and CD8+ effector T cells with reduced number of Tregs, IL-10+ Tr1, and IL-10+ CD8 T cells within the tumors." (PMID 32132993, 2020). "Interleukin-6 (IL-6), IL-10, and TNF are important triggers of myeloid origin inhibiting the proliferation and recruitment of MDSCs and are considered to be the main coordinator of immunosuppressive tumor microenvironment." (PMID 32547401, 2020). "Nevertheless, in various cancers, the tumor cells expressed various cytokines, for instance, transforming growth factor beta (TGF-β), vascular endothelial growth factor (VEGF), interleukin-10 (IL-10), macrophage colony-stimulating factor (M-CSF), which blunt various functions of dendritic cells." (PMID 32911646, 2020). "Dysplasia and tumour incidence were less prominent in probiotic-treated animals, as was the expression of proliferation markers and pro-inflammatory cytokines and COX-2, while regulatory IL-10 levels increased." (PMID 32575876, 2020). "Efforts to detect IL-10 expression by the tumor infiltrating NKT cells were not, however, successful." (PMID 32127556, 2020). "Cytokines are a family of soluble factors, classified into growth factors, chemokines, angiogenic factors and interferons and involved in tumor immune-landscape, by exerting pro- (IL-1β, IL-6, IL-8, and macrophage migration inhibitory factor—MIF) and anti-inflammatory (IL-10 and TGF-β) functions." (PMID 32012917, 2020). "IL-10 and TGF-β, together with IL-6 released in the TME, also inhibit natural killer (NK) and natural killer T (NKT) cells, therefore reducing their potent killing activity against tumor cells." (PMID 32235370, 2020). "In an immunosuppressed tumor microenvironment, γδ T cells show impaired IFN-γ production and degranulation (perforin and CD107a) capacity, which is attributed to the secretion of TGF-β and IL-10 by tumor-infiltrating Tregs." (PMID 33597951, 2020). "As in the tumor tissues, IFNγ, IL-10, IL-17A, and IL-4 were measured and similar to tumor tissues, in vitro culture of T cells were found to have significantly increased levels of IFNγ and IL-17A, with G-CSFR−/− CD4+ T cells, while IL-10 and IL-4 levels were decreased compared to WT." (PMID 33042110, 2020). "Moreover, the levels of IL-10 and ARG-1 mRNA in tumor tissue as markers for M2 protumor macrophages were assessed by RT-qPCR." (PMID 32340166, 2020). "We cannot exclude other mechanisms of inflammation-induced tumor formation in the colon since colitic IL10−/− mice treated with antioxidants or L-NIL had higher polyp counts than non-colitic IL10−/− mice." (PMID 32286276, 2020). "If the IL-2 effect consists in the activation of the host immune system, the role of IL-10 is not so clear, as IL-10 is a pleiotropic cytokine that at low concentrations exhibits tumor-promoting activity, while at high levels it shows an anti-tumor effect." (PMID 32013102, 2020). "Mice treated with CpG plus anti-IL-10Rα have dramatically reduced C26 colon carcinoma growth, while anti-IL-10R or CpG alone does not, indicating blockade IL-10 signaling pathway together with TLR-9 stimulation promotes tumor rejection." (PMID 32670290, 2020).
tumor (continued). "Moreover, the immune checkpoints B7-H3/CD276 and OX40 were found to be significantly co-expressed with core EMT genes, TGFB1, CXCR4, IL10, and IL6 on tumor microenvironment as vascular endothelial and myeloid cells." (PMID 32708431, 2020). "We speculated that, like Tfh‐like cells, AITL tumor cells suppressed the conventional CD4+ T cells, via IL10 and transformin growth factor β (TGF‐β)." (PMID 31793218, 2020). "Tumor-derived exosomes were shown to mediate the conversion of CD4+ CD25− T cells into CD4+ CD25high FOXP3+ regulatory T cells with enhanced expression of Fas ligand, IL-10, TGF-β1, CTLA-4, granzyme B, and perforin." (PMID 32499786, 2020). "PCa tumours which have metastasized to the bone have been reported to be infiltrated by immune cells which may be the source of IL6 and/or IL10." (PMID 32802517, 2020). "Unlike the anti-tumour M1, M2 express high levels of IL-10 and low levels of IL-12, and are known to enhance tumour progression." (PMID 32931721, 2020). "In agreement, the IL-10/IL-12 ratio, a critical parameter used to evaluate tolerogenic and immunoregulatory phenotypes, was not altered in tumor CM." (PMID 33202705, 2020). "In our data, although there were high levels of pro-inflammatory cytokines in the re-stimulated splenocytes (IL-12p70 and IFN-γ) and single tumor cells (IFN-γ), the levels of anti-inflammatory cytokines (IL-10) in the re-stimulated splenocytes and single tumor cells were also increased." (PMID 32733437, 2020). "IDO and TDO are highly expressed in tumor cells and can promote the recruitment of Tregs in the TME and induce immunosuppression via increased secretion of the immunosuppressive factors IL-6, IL-10, and TGF-β,93–95 which can help tumors achieve TIE." (PMID 32561709, 2020). "Moreover, we further found that the expression of iNOS mRNA and TNF-α mRNA were decreased in tumor tissues, while CD206 mRNA and IL-10 mRNA were increased." (PMID 32595415, 2020). "IL10 predominantly displays a tumor-inhibiting activity through the activation of NK cells, enhancement in surface expression of MHC antigen and promoting tumor infiltration by neutrophil and macrophages." (PMID 32300557, 2020). "This might reflect a reduced inflammatory state and/or a reduced release of IL‐10 by RAGE‐negative TAMs in LLC masses leading to increased survival, as reported in other tumour types." (PMID 32159297, 2020). "T cells cocultured with IL-10-stimulated cells of K1 and TPC-1 exhibited increased cell activation (%CD25+ of CD3+ T cells) and IL-2 production at an E:T ratio of 30:1, which was evidence for promotion in tumor immunity in PTC." (PMID 32348468, 2020). "Tumor infiltrated Treg cells and M2 macrophages significantly correlate with the tumor suppressive system in STAD as they produce cytokines such as transforming growth factor beta 1 (TGF-β1), interleukin-10 (IL-10), and colony stimulating factor 1 (CSF1)." (PMID 32408477, 2020). "Vitamin D compounds did not affect the concentration of TGF-β and IL-10 in the tumor and TGF-β in the plasma tissues." (PMID 32887237, 2020). "Several cytokines, which can arise from either tumor cells or immunocytes, such as tumor necrosis factor (TNF)-α, interleukin (IL)-1β, IL-6, IL-8, IL-10, and vascular endothelial growth factor (VEGF), have been linked with cancers and can either promote or inhibit tumor development." (PMID 32847533, 2020). "However, prolonged production of IL-10 in the TME is a potent promoter of cancer as it contributes to the constitutive activation of STAT3 in immune cells and tumor cells, thereby restraining the anti-cancer immune responses and driving oncogenic signaling." (PMID 31936322, 2020). "In vitro, M‐CSF, TGF‐β and VEGF from primary tumor supernatants skewed the differentiation of healthy donor blood monocytes towards CD163highCD86lowIL‐10high M2‐like MΦ that strongly suppressed CD4+ T‐cell expansion via PD‐L1 and IL‐10." (PMID 32082570, 2020).